KIAA0513 (KIAA0513)
Tractability: PROTAC: its protein half-life has been measured.
Gene: Protein-coding gene on chromosome 16 (85,027,709 to 85,094,230, forward strand). Ensembl gene ENSG00000135709.
Subcellular location: Cytoplasm
Subcellular location (Human Protein Atlas): Cytosol
Gene Ontology:
Cellular component: cytoplasm
Genetic constraint (gnomAD): Loss-of-function variants: 37 observed, 52.22 expected, observed/expected ratio (o/e) 0.71, 90% interval 0.54 to 0.93. The upper end of that interval is the gene's LOEUF score, 0.93, which puts it in group 3 of 6, group 1 being the genes least tolerant of losing a copy. Missense variants: 576 observed, 539.48 expected, observed/expected ratio (o/e) 1.07, 90% interval 1 to 1.14. Synonymous variants: 264 observed, 221.72 expected, observed/expected ratio (o/e) 1.19, 90% interval 1.08 to 1.32.
Homologues: Orthologues: chimpanzee KIAA0513 (99% identical), macaque KIAA0513 (98% identical), dog KIAA0513 (90% identical), mouse 6430548M08Rik (89% identical), rat 6430548M08Rikl (89% identical), pig KIAA0513 (87% identical), guinea pig KIAA0513 (86% identical), tropical clawed frog KIAA0513 (74% identical), rabbit KIAA0513 (73% identical), zebrafish kiaa0513 (65% identical), Drosophila melanogaster CG17378 (30% identical).
Diseases named in the same sentence as KIAA0513 in open-access papers:
KIAA0513 is named in the same sentence as 25 diseases in open-access papers, as found by Europe PMC text mining. Sharing a sentence is not in itself a finding about the gene and the disease. The quoted sentences say what the papers report.
Alzheimer disease (2 papers, 2020 to 2024). A progressive, neurodegenerative disease characterized by loss of function and death of nerve cells in several areas of the brain leading to loss of cognitive function such as memory and language. "The human ortholog of Krang, KIAA0513 (71% identity), has been predicted to function during neural development and its transcript to be dysregulated in individuals with schizophrenia and Alzheimer’s Disease." (PMID 39052672, 2024).
chronic kidney disease (2 papers, 2024). Impairment of the renal function secondary to chronic kidney damage persisting for three or more months. "Here, we report on serum antibodies against KIAA0513 (s-KIAA0513-Ab) as a broad-spectrum biomarker applicable to atherosclerosis-related diseases such as ischemic stroke, cardiovascular disease (CVD), chronic kidney disease (CKD), DM and solid cancers." (PMID 38983794, 2024).
Hypertension (2 papers, 2024). The presence of chronic increased pressure in the systemic arterial system. "Among these mRNAs, ARID3A, LRPAP1, and KIAA0513, along with hsa-miRNA-5589–5p, demonstrated associations with hypertension." (PMID 38836231, 2024). "KIAA0513 has been linked to neuroplasticity, which can contribute to hypertension." (PMID 38836231, 2024). "In conclusion, these results indicate that mRNAs KIAA0513, LRPAP1, ARID3A, and hsa-miRNA-5589–5p can be considered as diagnostic biomarkers for patients with hypertension." (PMID 38836231, 2024). "The close association between s-KIAA0513-Ab levels and hypertension could account for the association with OSAS, which is frequently accompanied by hypertension." (PMID 38983794, 2024). "Notably, this analysis revealed that LRPAP1, ARID3A, and KIAA0513 may have the potential to influence hypertension." (PMID 38836231, 2024). "While miRNA-mRNA networks have previously been utilized to detect markers for various diseases, including hypertension, the regulatory networks involving LRPAP1, KIAA0513, and ARID3A have been less explored." (PMID 38836231, 2024). "A significant difference in the s-KIAA0513-Ab levels was observed only between the patients with hypertension and those without hypertension." (PMID 38983794, 2024).
pancreatic cancer (2 papers, 2019 to 2022). "In conclusion, on the basis of TCGA sequence data, we proposed a four genes model (DNAH10, HSBP1L1, KIAA0513, and MRPL3), which facilitated the discernment of high‐risk patients for worse OS in pancreatic carcinoma." (PMID 31102348, 2019). "Functional analysis indicated KIAA0513 participated into the neuroplasticity, apoptosis, and cytoskeletal regulation, and it was therefore reasonable that the gene seemed to represent the neuro‐endocrine activity in pancreatic cancer." (PMID 31102348, 2019). "Out of 11 ITGA3, MET, FNDC3B, PPP1R14B and KIAA0513, including PLAU, were previously reported as individual prognostic markers in the pancreatic cancer TCGA-PAAD cohort." (PMID 36591282, 2022).
atherosclerosis (1 paper, 2024). A disease characterized by the build-up of fatty material and calcium deposition in the arterial wall resulting in partial or complete occlusion of the arterial lumen. "Spearman's correlation analysis revealed that serum anti-KIAA0513 antibody levels were associated with maximum intima-media thickness and plaque score, which are indices of atherosclerosis and stenosis." (PMID 38983794, 2024). "The correlation with max-IMT suggests that the s-KIAA0513-Ab levels are associated with stenosis and atherosclerosis, which was further confirmed by using other cohorts." (PMID 38983794, 2024). "In the present study, the initial screening using the protein array method identified KIAA0513 as an antigen recognized by serum IgG antibodies in patients with atherosclerosis." (PMID 38983794, 2024). "In the present study, the initial ProtoArray screening identified KIAA0513 as an antigen, as recognized by serum IgG in patients with atherosclerosis, and subsequently recombinant GST-tagged KIAA0513 protein of 301 amino acids was purified." (PMID 38983794, 2024). "In conclusion, the serum anti-KIAA0513 antibody marker appears to be useful for diagnosing the progress of atherosclerosis, which can lead to the onset of life-threatening AIS, CVD and cancer." (PMID 38983794, 2024). "Spearman's correlation analysis revealed a significant correlation between s-KIAA0513-Ab and max-IMT, plaque score and CAVI, all of which are indices of atherosclerosis-related lesions (Tables II and SVIII)." (PMID 38983794, 2024).
cerebrovascular disease (1 paper, 2024). "Notably, cancer, heart disease, cerebrovascular disease, renal failure and DM can be detected by the s-KIAA0513-Ab marker, making it applicable for diagnostic purposes and providing appropriate treatment, lifestyle guidance, etc., leading to improved quality of life." (PMID 38983794, 2024).
COVID-19 (1 paper, 2024). A disease caused by infection with severe acute respiratory syndrome coronavirus 2. "The s-KIAA0513-Ab marker is therefore a highly useful tool for detecting patients with COVID-19 who are at a higher risk of mortality." (PMID 38983794, 2024).
dementia (1 paper, 2024). Loss of intellectual abilities interfering with an individual's social and occupational functions. "A study employed the ComBat method to integrate gene expression data associated with presenile dementia and identified five genes, including KIAA0513, related to the disease through weighted gene co-expression network analysis in a mouse model." (PMID 39766789, 2024).
esophageal cancer (1 paper, 2024). A primary or metastatic malignant neoplasm involving the esophagus. "A receiver operating characteristic (ROC) analysis revealed that the highest areas under the ROC curves of anti-KIAA0513 antibodies were obtained for esophageal cancer, nephrosclerosis-type CKD and DM." (PMID 38983794, 2024).
neuroblastoma (1 paper, 2019). Neuroblastoma (NB) is the most common solid, extracranial childhood tumor. "CACNA1B overexpression is associated with an unfavorable prognosis in non-small cellular lung cancer and altered expression of KIAA0513, due to an aberrant methylation pattern, correlated with non-survivors in Neuroblastoma." (PMID 31249626, 2019).
cancer (3 papers, 2016 to 2024). A tumor composed of atypical neoplastic, often pleomorphic cells that invade other tissues. "Five genes were located in four of the seven breakpoint regions and three of these genes (CACNA1B, C8orf33 and KIAA0513) are associated with cancer." (PMID 31249626, 2019).
tumor (2 papers, 2016 to 2022). "In seven out of eight tumor entities, the gene KIAA0513 was found to be concerned." (PMID 27391163, 2016).
KIAA0513 also shares sentences with these, for which no sentence is quoted: breast carcinoma (1 paper); cardiovascular disease (1); diabetes mellitus (1); glioblastoma (1); heart disease (1); ischemic stroke (1); mild cognitive impairment (1); nephrosclerosis (1); obstructive sleep apnea syndrome (1); renal failure (1); retinoblastoma (1); schizophrenia (1); transient ischemic attack (1).